COL8A1 (collagen type VIII alpha 1 chain)
Diseases named in the same sentence as COL8A1 in open-access papers (continued):
Sharing a sentence is not in itself a finding about the gene and the disease.
atherosclerosis (5 papers, 2018 to 2025). A disease characterized by the build-up of fatty material and calcium deposition in the arterial wall resulting in partial or complete occlusion of the arterial lumen. "Given the role of Collagen VIII in neovascularization and its association with atherosclerosis, altered expression of Col8a1 and Col8a2 in progenitors could represent a mechanistic target in aortic disease." (PMID 40277904, 2025). "Increased COL8A1 levels are observed during the development of atherosclerosis or after injury and are known to favor cancer progression." (PMID 34777248, 2021). "Among the top 10 significantly enriched genes of Dkk2hi ECs, Ngf, Col8a1, Kit, and Vcan were reported to be involved in the development of atherosclerosis." (PMID 34282126, 2021). "Additionally, a cell population co-expressing contractile genes with key ECM genes (Col1a1, Mgp, Eln, Fn1, Col4a1, and Col8a1) and Notch3, mapped together with the fcVSMC population from the atherosclerosis dataset (I-cluster 6)." (PMID 40577585, 2025). "An unannotated disease-specific cell cluster (A-cluster 6) co-expressed contractile VSMC markers (Myh11, Acta2, and Cnn1) with several atherosclerosis-induced ECM genes (Col1a1, Mgp, Eln, Fn1, Col4a1, and Col8a1) and had reduced levels of Ly6a, Vcam1, and Tnfrsf11b compared to imVSMCs." (PMID 40577585, 2025).
cervical carcinoma (4 papers, 2019 to 2023). A carcinoma arising from either the exocervical squamous epithelium or the endocervical glandular epithelium. "Collagen members, including COL6A3, COL5A1, and COL8A1, act as oncogenes in the progression of different types of cancer and are highly correlated with poor prognosis in cervical cancer patients." (PMID 32523603, 2020). "COL8A1 has been shown to promote non-small cell lung cancer progression by activating IFIT1/IFIT3-mediated EGFR signaling, while FABP5 can promote lymph node metastasis in cervical cancer by reprogramming fatty acid metabolism." (PMID 37795080, 2023).
colon adenocarcinoma (4 papers, 2018 to 2023). "It is suggested that COL8A1 may be associated with malignant processes of hepatocarcinoma and the progression and prognosis of human colon adenocarcinoma." (PMID 33282565, 2020). "Furthermore, in colon adenocarcinoma, COL8A1 was shown to play a role in the tumor progression possibly by mediating focal adhesion-related pathways." (PMID 37188982, 2023). "Moreover, a latest study based on co-expression network analysis observed that overexpression of COL8A1 is relevant to the adverse prognosis of human colon adenocarcinoma." (PMID 30065754, 2018).
colorectal cancer (4 papers, 2020 to 2024). A primary or metastatic malignant neoplasm that affects the colon or rectum. "COL8A1 may affect the progression of colorectal cancer and the prognosis of patients by regulating focal adhesion-related pathways, and the expression of COL8A1 in colorectal cancer is related to the expression of Wnt2 and is linked to the poor survival of patients." (PMID 35774273, 2022).
glioma (4 papers, 2022 to 2025). A benign or malignant brain and spinal cord tumor that arises from glial cells (astrocytes, oligodendrocytes, ependymal cells). "In conclusion, our work unveils COL8A1 as a central node in a pathogenic network that drives glioma aggressiveness by synchronizing tumor-intrinsic inflammation with the sculpting of an immunosuppressive TME." (PMID 41451204, 2025). "We next assessed the association between COL8A1 expression and genomic alterations in glioma." (PMID 41451204, 2025). "The mutational landscape analysis further contextualizes COL8A1 within glioma molecular subtypes." (PMID 41451204, 2025). "This study systematically identifies and validates COL8A1 as a pivotal inflammatory hub that bridges tumor-intrinsic properties, immune surveillance, and therapy response in glioma." (PMID 41451204, 2025). "By connecting tumor-intrinsic inflammation to immunological surveillance and treatment resistance, our study identified COL8A1 as a crucial inflammatory hub in glioma." (PMID 41451204, 2025). "This solidifies COL8A1’s potential utility as a novel biomarker for patient selection in glioma immunotherapy." (PMID 41451204, 2025). "In every cohort, patients with high COL8A1 expression exhibited significantly worse overall survival, unequivocally establishing COL8A1 as a robust and reproducible poor prognostic factor in glioma." (PMID 41451204, 2025). "Aberrant expression of COL8A1 has been reported in several cancers; however, its role in glioma, particularly its connection to the inflammatory TME and immune regulation, remains largely unexplored." (PMID 41451204, 2025). "Showed that patients with high Parthanatos scores had a poorer prognosis and that the viability, proliferation, invasion, and migration of glioma cells were significantly inhibited by silencing the Parthanatos-related gene COL8A1." (PMID 38730061, 2024). "Our Kaplan–Meier analysis demonstrated that high expression of COL1A1, COL1A2, COL3A1, COL5A1, COL8A1, ELN, FN1 resulted in lower OS in all grade glioma patients, in turn causing poor prognosis." (PMID 36106447, 2022). "In glioma, our research methodically identified COL8A1 as a unique inflammatory center." (PMID 41451204, 2025). "In order to improve the results of immunotherapy for glioma, COL8A1 may be a useful therapeutic target and prognostic biomarker." (PMID 41451204, 2025). "In addition, temozolomide acting on glioma cells can effectively inhibit the expression of COL8A1, thus improving the malignant characterization of the cells." (PMID 38730061, 2024).
liver fibrosis (4 papers, 2015 to 2025). "SWT collectively ameliorated liver fibrosis by inhibiting the COL8A1/IL-1β/OLR1 pathways associated with LSEC angiogenesis, adhesion and defenestration, as well as suppressing LSEC secretion of IL-1β to reduce HSC activation." (PMID 39741334, 2024). "Overall, our findings suggested that SWT restored liver sinusoidal permeability and alleviated the progression of liver fibrosis by inhibiting COL8A1/IL-1β/OLR1 conducted LSEC angiogenesis, adhesion and defenestration." (PMID 39741334, 2024). "Taken together, these findings suggested that SWT might ameliorate hepatic fibrosis by potentially inhibiting the adhesive process mediated by COL8A1, the angiogenesis process mediated by IL-1β and the LCEC defenestration mediated by OLR1." (PMID 39741334, 2024). "It was shown that a lack of collagen VIII reduces myofibroblast differentiation and fibrosis in mouse hearts, and that COL8A1 and COL5A2 are dysregulated in progressing liver fibrosis in rodents." (PMID 39466591, 2024). "Previous researches have suggested that COL8A1, IL-1β and OLR1 were involved in the process of liver fibrosis." (PMID 39741334, 2024). "However, the functions of COL8A1 and OLR1 in LSECs during liver fibrosis were not clear." (PMID 39741334, 2024).
Stroke (4 papers, 2012 to 2024). Sudden impairment of blood flow to a part of the brain due to occlusion or rupture of an artery to the brain. "COL8A1 is also one of the “sprouting angiogenesis” genes with delayed expression after stroke in aged rats, providing a link to choroidal angiogenesis." (PMID 32789304, 2020). "However, one third of the genes were increased with suboptimal timing in aged rats, either on day 3 post-stroke (Adam17, Gpc3, Mmp14, Nid2, Tagln, Wnt5b) or on day 14 after stroke (Col4a2, Col8a1, Cthrc1, Cxcl1, Gpc3, Tgfbr2)." (PMID 23251410, 2012).
colon cancer (3 papers, 2019 to 2024). "Although contribution of the differential TME components to patient prognosis remains elusive, our current study proposed that CAF activation represented by COL8A1 in addition to CTL activation reflected by CD8A are critical determinants of prognosis in colon cancers." (PMID 38557819, 2024). "There are only a limited number of studies that have investigated the role of COL8A1 in cancer, but COL8A1 expression has been reported to be correlated with the progression and prognosis of colon cancer and knockdown of COL8A1 reduces invasion in hepatocarcinoma cells." (PMID 31717573, 2019).
Hypertension (3 papers, 2016 to 2025). The presence of chronic increased pressure in the systemic arterial system. "We found that in the univariate analysis that both single-nucleotide polymorphisms in COL8A1 gene (rs13095226 and rs669676) together with age, sex and hypertension were significantly associated with myopic CNV development in Spanish patients (p<0.05)." (PMID 27643879, 2016). "Salmons seem to be a good food resource for people to treat hypertension or improve health, and collagen subunit proteins col4a5 and col8a1 are potent antihypertensive agent substitutes for existence of numerous ATHPs in their sequences." (PMID 30279337, 2018).
lung carcinoma (3 papers, 2019 to 2022). "Col4a3 expression is associated with the poor prognosis of lung cancer patients after receiving chemotherapy, and Col8a1, Col5a3, and Col15a1 are involved in tumor growth and development." (PMID 35565312, 2022). "Further, to explore the mechanisms of COL8A1 promoted lung cancer development, we found COL8A1 activated EGFR via upregulation of IFIT1 and IFIT3." (PMID 35280763, 2022).
pancreatic cancer (3 papers, 2012 to 2025). "We found that Ccn1‐deficient pancreatic cancer cells exhibit reduced expression of collagens, including Col4a1, Col4a2, Col5a1, Col6a1, Col6a2, Col6a3, and Col8a1." (PMID 40287974, 2025). "Similarly, mRNA levels of Col5a1, Col6a1, Col6a2, Col6a3, and Col8a1 were significantly reduced in Ccn1‐deficient pancreatic tumors, while Col4a1 and Col4a2 were unaffected." (PMID 40287974, 2025).
psoriasis (3 papers, 2019 to 2021). An autoimmune condition characterized by red, well-delineated plaques with silvery scales that are usually on the extensor surfaces and scalp. "We observed significant increases in protein expression of CMKLR-1, COL8A-1, NRK, and SYTL-2 in DMSCs from patients with psoriasis compared with those from healthy donors, whereas the expression level of SFRP-2 was obviously decreased." (PMID 30760317, 2019). "We observed the upregulation of CMKLR-1, COL8A-1, NETO-2, NRK, SYTL-2, and SULF-2 in dermal mesenchymal stem cells derived from patients with psoriasis at both mRNA and protein level, however, a significant downregulation of SFRP-2 between two groups." (PMID 30760317, 2019).
asthma (2 papers, 2021 to 2023). "In our study, we have investigated the association of SNPs in three collagen-coding genes, Col3A1/rs1800255, Col6A5/29rs12488457, and Col8A1/rs13081855, with the clinical manifestations of AD as well as the coexistence of asthma." (PMID 37109047, 2023).
bladder cancer (2 papers, 2019 to 2021). "COL5A1, COL8A1 were most significant in the prediction of the bladder cancer’s prognosis(P-value< 0.01), and may serve as the therapeutic target for the disease." (PMID 30723390, 2019). "As such, COL5A1, COL8A1 and TGFB1I1 can serve as the prognosis biomarkers for patients of bladder cancer." (PMID 30723390, 2019). "Among the main repressed genes in bladder cancer, there are fatty acid binding protein 4 (FABP4) and fibroblast growth factor binding protein 1 (HBP17), RGS4, tissue inhibitor of metalloproteinase 3 (TIMP3), WNT5b, URB, and collagen type VIII, alpha 1 (COL8A1)." (PMID 34835969, 2021).
cardiac hypertrophy (2 papers, 2020 to 2022). "Consistently, B38-CAP treatment significantly downregulated increased expression of mRNA associated with the pathology of cardiac hypertrophy (BNP and β-myhc) and fibrosis (Col8a1, Postn, and Tgfb2)." (PMID 32103002, 2020). "Next, we measured genes typically upregulated in pathological cardiac hypertrophy: genes regulating collagen synthesis (Col1a1, Col3a1, Col8a1, and Ccl2) were not altered by diet." (PMID 35736495, 2022).
choroidal neovascularization (2 papers, 2019 to 2020). An eye disorder described by the growth of new blood vessels that originate from the choroid through a break in the Bruch membrane into the sub–retinal pigment epithelium (sub-RPE) or subretinal space. "The genetic analysis showed that COL8A1 SNP rs13095226 was associated with the development of choroidal neovascularization (CNV) and also seems to play an important role in the increase of axial length." (PMID 32730261, 2020). "As in non-AMD patients, one of the common variants in COL8A1 gene (rs669676) was found to be associated with myopic choroidal neovascularization (OR: 1.88; 95% CI: 1.18-2.98, p = 0.0076) but did not survive multiple testing." (PMID 31191752, 2019).
diabetes (2 papers, 2023). "In addition, our studies found that TSP1 targets included: TAGLN, a regulator of angiogenesis, LOXL4, a contributor to the vascular permeability in diabetes, types of collagen (COL4A1 and COL8A1) that influence angiogenesis plus THSB1 an inhibitor of angiogenesis." (PMID 36949528, 2023).
endometriosis (2 papers, 2021 to 2023). The growth of functional endometrial tissue in anatomic sites outside the uterine body. "Previous microarray studies on gene expression profiles have shown that miR-210 and its downstream targets (IGFBP3 and COL8A1) play a role in pathophysiology of endometriosis, but the underlying mechanisms remain unclear." (PMID 37188982, 2023). "Finally, although we demonstrated changes in the expression of COL8A1, the molecular mechanisms underlying its role in endometriosis remain unclear." (PMID 37188982, 2023). "To identify the cell-specific localization of IGFBP3 and COL8A1 in vivo, we performed immunohistochemistry on matched mid-secretory EuE and EcE of women with endometriosis." (PMID 37188982, 2023). "Previous studies revealed the role of collagen I in EuE and EcE; hence, this study was the first to show the in vivo characterization of COL8A1 in endometriosis." (PMID 37188982, 2023). "Given the consistent upregulation of COL8A1 in endometriotic lesions from humans and baboons with endometriosis, the role of COL8A1 in endometriosis will be worth exploring." (PMID 37188982, 2023). "To explore the characterization of IGFBP3 and COL8A1 in vivo, we performed RT-qPCR on matched mid-secretory EuE and EcE from baboons and women with endometriosis." (PMID 37188982, 2023). "In addition, some identified hub genes of the EC (TAGLN, GATA6, CDH3, CLU, COL8A1, MYH11, MYOCD) and EU (CXCL13, DDK-1, KLF4, CYP2E1, CYP4B1 and PROK1) have been reported be associated with endometriosis." (PMID 34522169, 2021).
gastric adenocarcinoma (2 papers, 2022). "Altogether, our bioinformatics analysis study identified six upregulated DEGs (ADAMTS2, COL10A1, COL1A1, COL1A2, COL8A1, and BGN) between gastric adenocarcinoma and normal tissues based on four different microarray datasets." (PMID 35726219, 2022). "Furthermore, studies have demonstrated the close relation between collagen genes and gastric adenocarcinoma, including COL10A1, COL1A1, COL1A2, and COL8A1." (PMID 35726219, 2022).
triple-negative breast carcinoma (2 papers, 2019 to 2023). An invasive breast carcinoma which is negative for expression of estrogen receptor (ER), progesterone receptor (PR), and human epidermal growth factor receptor 2 (HER2). "Another study of triple-negative breast cancer showed a more aggressive phenotypic transformation with enhanced FAK/Src activation through COL8A1 overexpression." (PMID 36840005, 2023).
abdominal aortic aneurysm (1 paper, 2022). Enlargement and ballooning of the vessel that supplies arterial blood to the abdomen, pelvis and legs. "IF staining demonstrated the colocalization of COL8A1 and αSMA in phenotypic-transformed SMCs in mouse thoracic and abdominal aortic aneurysms, but COL8A1 was not expressed in contractile smooth muscle." (PMID 36703732, 2022).
amoebiasis (1 paper, 2022). "The prime module in protein-protein interaction network of DEGs, including ADAMTS2, COL10A1, COL1A1, COL1A2, COL8A1, BGN, and SPP1, was enriched in protein digestion and absorption, ECM-receptor interaction, focal adhesion, PI3K-Akt signaling pathway, and amoebiasis." (PMID 35726219, 2022).
Arrhythmia (1 paper, 2015). Any cardiac rhythm other than the normal sinus rhythm. "Moreover, calcium handling and contractile function genes (SLN, ACTC1, PLCD4, PLCZ), potential arrhythmia-related genes (MYO5B, KCNA5), and cytoskeleton and cellular organization-related genes (XIRP2, COL8A1, KCNA6) were among the most deregulated genes in rTOF ventricles." (PMID 26252659, 2015).
astrocytoma (1 paper, 2025). "We also detected increased COL8A1 transcript expression in GBM versus grade III astrocytoma via FeaturePlot visualization of normalized gene expression." (PMID 41366031, 2025). "Among the 19 collagen gene transcripts that were profiled, COL16A1, COL8A1, and COL2A1 exhibited higher levels in the GBM tissue versus the grade III astrocytoma sample." (PMID 41366031, 2025). "Similarly, unlike in grade III astrocytoma, COL8A1 transcripts showed enhanced expression primarily in perivascular MG/MØs in GBM." (PMID 41366031, 2025).
brain tumor (1 paper, 2021). "It is very interesting to note that the concomitant upregulation of COL8A1, COL6A2 and COL6A3 has been identified as part of the adamantinomatous craniopharyngioma signature, an aggressive rare pediatric brain tumor in which calcifications are a diagnostic hallmark." (PMID 34777248, 2021).
cervical dystonia (1 paper, 2021). "For example, SNPs in COL8A1, DENND1A, and GABBR2 were found to be associated with cervical dystonia in a multicenter GWAS." (PMID 35273550, 2021).
corneal dystrophies (1 paper, 2023). "Likewise, for COL8A1, an ECM component linked to AMD and to corneal dystrophies, 4 sites were bound by both OTX2 and LHX2 and 3 only by OTX2." (PMID 36649236, 2023).
corneal endothelial dystrophies (1 paper, 2026). "Dysregulation of Col8a1 and Col8a2 is implicated in a broad spectrum of disorders, including vascular remodeling, tissue fibrosis, diabetic nephropathy, cancer progression, and corneal endothelial dystrophies." (PMID 41641337, 2026).
geographic atrophy (1 paper, 2015). "The T allele of rs1883025 in ABCA1 is associated with a decreased risk of intermediate drusen, large drusen, geographic atrophy (GA) and neovascularization, whereas the C allele of COL8A1 is protective of the transition from intermediate to large drusen." (PMID 25893111, 2015).
gingival fibromatosis (1 paper, 2021). "In ERS GFs, MMP2 protein and MMP2 mRNA level were 3-fold increased both at the protein (CM) and transcript levels (cell lysates) suggesting that increased expression of COL8A1 and MMP2 would contribute to the pathogenesis of gingival fibromatosis." (PMID 34777248, 2021).
heart failure (1 paper, 2024). Inability of the heart to pump blood at an adequate rate to meet tissue metabolic requirements. "Our results suggest that COMP, COL8A1, LOX, and ACOT1 warrant further investigation in the development of cardiac fibrosis and as potential biomarkers for causing heart failure." (PMID 38854759, 2024). "Overexpression of lysine-specific demethylase 3A (KDM3A) leads to the up regulation of fibrosis-related genes COMP, COL8A1, and LOX and the down regulation of ACOT1, result in enhanced fibrosis and heart failure." (PMID 38854759, 2024).
ischemic cardiomyopathy (1 paper, 2016). Ischemic cardiomyopathy is a cardiomyopathy in which a weakness in the muscle of the heart due to inadequate oxygen delivery to the myocardium with coronary artery disease being the most common cause. "We carried out RT-qPCR and western blot analyses focusing on COL8A1, related significantly with LV mass index, and on COL16A1, the new collagen related with ventricular dysfunction in ischemic cardiomyopathy (ICM)." (PMID 27936202, 2016).
lung disease (1 paper, 2025). "Finally, to confirm an age association, we evaluated human lungs from aged (ages 73–76) and young (ages 31–45) individuals without known lung disease for COL8A1 protein expression in the airway epithelium." (PMID 41074556, 2025).